IDH1 (isocitrate dehydrogenase (NADP(+)) 1)
Diseases named in the same sentence as IDH1 in open-access papers (continued):
Sharing a sentence is not in itself a finding about the gene and the disease.
sarcoma (20 papers, 2015 to 2025). A usually aggressive malignant neoplasm of the soft tissue or bone. "Compelling evidences indicated that IDH1/2 mutation is sufficient to initiate enchondromas and sarcomas in vivo." (PMID 33413208, 2021). "Compelling evidence indicated that IDH1/2 mutation is sufficient to initiate enchondromas and sarcomas in vivo." (PMID 33413208, 2021). "The pleomorphic sarcoma with a concurrent IDH1 R132G mutation and a SUFU splice site mutation may indicate that the Hedgehog (Hh) pathway is operant in these cells independent of SHH ligand expression since SUFU is a negative regulator of Hh signaling." (PMID 32570879, 2020). "al. in 2014, vaccination of MHC-humanized mice with a peptide vaccine presenting amino acids 123–142 (p123–142) of IDH1 R132H was able to suppress the growth of a sarcoma with IDH1 R132H-positivity." (PMID 37371615, 2023). "A proof-of-concept study of IDH1 R132H peptide vaccines has been initiated in a humanized mouse sarcoma model." (PMID 31652645, 2019). "In this report, we have used sarcoma cell lines HT1080 and SW1353 that contain endogenous mutations of IDH1/2 to investigate the function of IDH mutation in tumorigenesis." (PMID 25825982, 2015). "On the other hand, the macrodissected WDCS and high-grade sarcoma components in DDCS cases showed similar methylation profiles, regardless of IDH1/IDH2 mutational status, suggesting that the observed IDH1/IDH2-associated methylation pattern is an early event in DDCS." (PMID 36926116, 2023). "Importantly, CD4+ T helper cell-mediated antitumor immunity is detected in subcutaneous IDH1 R132H sarcoma-bearing mice immunized with the mutant-specific peptide vaccination." (PMID 31652645, 2019). "Mutations of IDH1 or 2 have also been found in ~20 % AML and several subtypes of sarcomas." (PMID 27316347, 2016). "In two of the three cell lines analysed (DLD1 and RKO), both D- and L-2HG were elevated at levels comparable to or exceeding the concentrations measured in the sarcoma cell line HT1080, harbouring mutant IDH1." (PMID 27824159, 2016). "The peptide vaccine also inhibits the growth of IDH1(R132H) sarcomas without altering IDH1 wild-type enzymatic function." (PMID 40514725, 2025).
lung cancer (19 papers, 2018 to 2025). A malignant neoplasm involving the lung. "Further prospective studies in a larger cohort are warranted to elucidate if IDH1/2 mutations are markers for theranostics and/or prognostication in lung cancers." (PMID 32333643, 2020). "The combination of single biomarkers with high stage-specificity and histological type specificity (SHOX2 and PTGER4 DNA methylation and IDH1) showed better diagnostic performance in the detection of lung cancers compared with single marker assessment." (PMID 31888670, 2019). "Based on our previous study, the diagnostic effectiveness of IDH1 in lung cancers, especially in patients with Ade, has been validated." (PMID 31888670, 2019). "Although the incidence of IDH1/2 mutations is only 0.4%‐1.1% in NSCLCs, it is worthwhile to investigate IDH1/2 inhibitors because of the high prevalence of lung cancers in the United States and worldwide." (PMID 32333643, 2020). "Similar conditions in the validation group, i.e., significantly increased methylation levels of PTGER4 and elevated levels of IDH1, were observed in lung cancer patients compared with healthy controls (p < 0.05)." (PMID 31888670, 2019). "Among the individual biomarkers, IDH1 had the significantly highest AUC value compared with the two other methylation biomarkers in the group of early stage lung cancers." (PMID 31888670, 2019). "A study showed that knockdown of IDH1 by RNA interference reduced the proliferative capacity of NSCLC cells and significantly decreased in vivo xenograft tumor formation, suggesting that IDH1 may be a potential target in lung cancer." (PMID 33859940, 2021). "Therefore, further studies are needed to explore the reason for the high specificity of IDH1 in Ade lung cancers." (PMID 31888670, 2019). "Upregulation of IDH1 may be an adaptive alteration for lung cancer cells to antagonize and survive oxidative stress." (PMID 30634602, 2019). "Since the result of the low predictive value of individual candidate biomarkers could be enhanced by combination, IDH1 was chosen to construct a panel to discriminate lung cancers as a candidate biomarker of the most common lung Ade." (PMID 31888670, 2019). "Recently, IDH1 was reported to be up‐regulated in lung cancer tissues and could serve as novel plasma biomarker for the diagnosis of non‐small‐cell lung cancer." (PMID 29465809, 2018). "In addition, the levels of IDH1 in lung cancer patients were significantly elevated (p < 0.05)." (PMID 31888670, 2019). "IDH1 were selected as differential gene and enriched to reductive carboxylate cycle (CO2 fixation) pathway which is upregulated in lung cancer." (PMID 35261323, 2022). "Reductive glutamine metabolism has been reported to be highly dependent on the function of cytosolic IDH1, because the amount of [3-2H] glucose, which labels cytosolic NADPH, was reduced in lung cancer (H460) cells nullified for IDH1." (PMID 33808242, 2021). "The blood levels of individual biomarkers [IDH1, DNA methylation of short stature homeobox 2 gene (SHOX2), and prostaglandin E receptor 4 gene (PTGER4)] were measured and statistically analyzed in samples from healthy controls and patients with lung cancer." (PMID 31888670, 2019). "In lung cancer patients with KRAS WT, except for MTHFD1, the expression levels of G6PD, IDH1, and ME1 were not correlated with the patient survival time." (PMID 38997257, 2024). "In contrast with cytosolic IDH1, overexpression of IDH2 has not been described in patients with lung cancer." (PMID 30634602, 2019).
Maffucci syndrome (19 papers, 2013 to 2025). Maffucci syndrome is a very rare genetic bone and skin disorder characterized by multiple enchondromas, leading to bone deformities, combined with multiple dark, irregularly shaped hemangiomas or less commonly lymphangiomas. "Notable carcinogens include vinyl chloride and thorium dioxide, while NF-1 (neurofibromatosis), IDH1 (maffucci syndrome), and breast cancer gene (BRCA) 1 and 2 are associated genetic mutations." (PMID 40125238, 2025). "The majority of Maffucci syndrome cases are attributed to somatic mutations in the IDH1 gene, with a smaller proportion linked to IDH2 mutations." (PMID 40420921, 2025). "As IDH1 is strongly associated with Maffucci syndrome, the variant identified in this gene can explain this part of the phenotype." (PMID 38778413, 2024). "The literature describes that IDH1/2 mutations are frequently found in central and periosteal chondromas, often associated with Ollier’s disease and Maffucci syndrome." (PMID 38248076, 2024). "In summary, by a comparative analysis of exome sequences between peripheral blood DNA and enchondroma DNA in a patient with Maffucci’s syndrome, we identified an R132C mutation in the IDH1 gene and an L309I mutation in the ERC2 gene." (PMID 34790172, 2021). "It has been reported that somatic mosaic isocitrate dehydrogenase type 1 (IDH1) or isocitrate dehydrogenase type 2 (IDH2) mutations are associated with Maffucci’s syndrome." (PMID 34790172, 2021). "Collectively, these data suggest that the IDH1 R132C mutation combines with the ERC2 L309I mutation to cause the development of Maffucci’s syndrome." (PMID 34790172, 2021). "In a genetic study of various breast lesions, mutated tubular adenomas showed primarily mutations in MET and FGFR3, whereas enchondromas in Maffucci’s syndrome have been known to harbour isocitrate dehydrogenase (IDH1 and 2) mutations." (PMID 31585326, 2019). "A monoallelic point mutation of IDH1 is believed to be strongly correlated with tumorigenesis, which explains the development of multiple enchondromas, but the mechanisms underlying hemangiomas in Maffucci’s syndrome have yet to be elucidated." (PMID 34790172, 2021). "This supports the hypothesis that IDH1/2-mutations, which can be present in different types of tumor tissue simultaneously, arise during embryonic development in a mosaic pattern; as a result, a more aggressive follow-up is proposed in patients with Maffucci syndrome to exclude neoplasms." (PMID 26920730, 2016). "Heterozygous somatic mutations in the isocitrate dehydrogenase 1 and 2 (IDH1/IDH2) genes are associated with a number of different tumor types (e.g. IHCC) and also with Maffucci syndrome." (PMID 26920730, 2016). "Since the clinical manifestations of multiple enchondromas and SCHs raises the suspicion of Maffucci syndrome and the genetic analysis revealed somatic IDH1 p.Arg132Cys mutations in the SCH tissue and cystic blood samples, we diagnosed the patient with Maffucci syndrome." (PMID 35042566, 2022). "Therefore, our results suggest that the R132C mutation in IDH1 and the L309I mutation in ERC2 are probably the causative factors contributing to the development of Maffucci’s syndrome." (PMID 34790172, 2021). "The combination of the IDH1 R132C and ERC2 L309I mutations contributes to the development of Maffucci’s syndrome, and these results may enable further research on the pathogenesis of Maffucci’s syndrome." (PMID 34790172, 2021).
pilocytic astrocytoma (19 papers, 2009 to 2025). Pilocytic astrocytoma is a rare subtype of low-grade glioma of the central nervous system characterized by a well circumscribed, often cystic, brain tumor with a discrete mural nodule and long, hair-like projections that extend from the neoplastic astrocytes. "Presumably, the number of patients with IDH1-wild-type tumors with younger average age (i.e., pilocytic astrocytoma, ependymoma) was higher than that of those with primary GBM, thus lowering the total average age in this group." (PMID 32856857, 2020). "Furthermore, IDH1 or IDH2 mutations have not been identified in any pilocytic astrocytomas (WHO grade I), indicating a different tumorigenic mechanism." (PMID 40103938, 2025). "CNS_099, initially diagnosed as pilocytic astrocytoma, was reclassified as adult‐type diffuse high‐grade glioma, IDH‐wildtype, and subtype E. WES sequencing did not identify mutations in IDH1/2, corroborating the methylation‐based classification." (PMID 41033792, 2025).
thyroid cancer (19 papers, 2013 to 2025). "In TC, among those over-expressed in males, we found PPARG, previously reported in thyroid carcinomas, ERCC5, MYH11, LEMD2, ZNF133, and IDH1, the latter found to be mutated in thyroid carcinomas." (PMID 32849808, 2020). "IDH1: Mutations in the isocitrate dehydrogenase 1 (IDH1) gene are highly prevalent in thyroid carcinoma (16%) in particular in FTCs (5%) and ATCs (11%)." (PMID 31540307, 2019). "For some of these mutants, a reduced enzymatic activity has been demonstrated, suggesting a potential tumorigenic role of the IDH1 system in thyroid cancer." (PMID 31540307, 2019). "The impact of the polymorphism in IDH1 (rs11554137) on survival has been investigated in AML and thyroid carcinoma." (PMID 24868540, 2014). "The results of this study allow us to conclude that low expression of MLH1 is associated with BRAF V600E mutations, RET/PTC rearrangements and transitions (IDH1 and NRAS) in patients with thyroid carcinoma." (PMID 23414134, 2013). "Taking these facts into consideration, the results of this study allow us to conclude that low expression of MLH1 is associated with BRAF V600E mutations and RET/PTC rearrangements and transitions (IDH1 and NRAS) in patients with thyroid carcinoma." (PMID 23414134, 2013). "Key metabolic regulators such as IDH1, PGAM1, NDUFS3, and LDHB were identified among these common genes, suggesting their central role in thyroid cancer metabolism." (PMID 40861812, 2025). "For instance, several genes such as IDH1 and PGAM1 displayed consistent alterations at the transcript, protein, and metabolite levels, indicating their critical role in reprogramming energy pathways like glycolysis and the TCA cycle in thyroid cancer." (PMID 40861812, 2025). "In addition to well-known BRAF, RAS, and RET mutations, NGS technology facilitated detection of new somatic alterations in thyroid cancer such as MITF, MDM2, JAK3, FLI1, IDH1 etc., all in which the significance of thyroid cancer has not been delineated yet." (PMID 27871285, 2016).
colon carcinoma (18 papers, 2016 to 2025). "IDH1/2 mutations have been observed in several solid and blood cancers including colon cancer." (PMID 30024920, 2018). "It should also be noted that there were colon cancer cell context-dependent differences in the effects of piperlongumine on downregulation of IDH-1 and TXNDC5." (PMID 37808182, 2023). "Using the developed SEC method, sEVs were collected from 200 mL culture supernatants from the wild-type and IDH1 mutant (R132H/+) strains of the colon cancer cell line HCT116." (PMID 36710884, 2022). "Using the developed SEC method, we recovered sEVs released by IDH1 mutant colon cancer cells and performed metabolomic analysis, which revealed a characteristic metabolomic profile, including high concentrations of 2-HG." (PMID 36710884, 2022). "Sirtuin 2 (SIRT2) mediates the deacetylation of isocitrate dehydrogenase (NADP (+)) 1 (IDH1), thereby, promoting IDH1 activity and the production of α-ketoglutarate (α-KG), inhibiting liver metastasis of colon cancer and improving prognosis." (PMID 35004688, 2021). "Recently, K224 acetylation in IDH1 was investigated in colon cancer and was shown to have an inhibitory role, though the consequences of K81 and K321 acetylation in IDH1 have yet to be explored." (PMID 34065652, 2021). "To test whether these findings could be seen in other cell lines with distinct mutations in the DDR pathway, we repeated the experiment in a matched pair of WT and IDH1 mutant cell lines in the HCT116 human colon cancer background." (PMID 41077566, 2025). "SIRT2 could deacetylate IDH1 at K224 and exhibit a tumor suppression function in a colon cancer cell model by inhibiting IDH1 enzymatic activity and the hypoxia-inducible factor 1α (HIF1α)-SRC transcription axis." (PMID 36577755, 2022). "Both IDH1 and TXNDC5 are regulated by NR4A1 in pancreatic and colon cancer cells, and knockdown of either NR4A1 or TXNDC5 in pancreatic cancer cells results in the induction of ROS." (PMID 27144436, 2016). "Treatment of the colon cancer cells with piperlongumine resulted in downregulation of IDH1 in RKO, SW480, and HCT116 (not significant) cells and selective downregulation of TXNDC5 in only SW480 cells." (PMID 37808182, 2023).
Alpha-thalassemia (17 papers, 2013 to 2025). Alpha-thalassemia is an inherited hemoglobinopathy characterized by impaired synthesis of alpha-globin chains leading to a variable clinical picture depending on the number of affected alleles. "A statistically significant association of methylated MGMT promoter was observed with isocitrate dehydrogenase-1 (IDH1) protein expression (p = 0.050) and alpha-thalassemia/mental retardation syndrome X-linked (ATRX) loss (p = 0.003)." (PMID 39760063, 2023). "Molecular markers of brain primary tumors such as O6-methylguanin-DNS-methyltransferase (MGMT), isocitratedehydrogenase-1 (IDH-1), and alpha-thalassemia/mental retardation syndrome X-linked (ATRX) have recently been shown to be correlated with chemotherapy response and prognosis." (PMID 33538882, 2021). "As tumor markers, we used antibodies against collapsin response-mediated protein 5 (CRMP5), alpha thalassemia/mental retardation syndrome X-linked (ATRX), and anti-isocitrate dehydrogenase 1 (IDH1)." (PMID 35740509, 2022). "IDH1 mutations are associated with alpha-thalassemia/mental retardation syndrome X-linked (ATRX) mutations and alternative lengthening of telomeres (ALT), suggesting an interaction between IDH1 and telomeres." (PMID 31960234, 2020). "Immunohistochemical staining revealed that the tumor cells were positive for GFAP, oligodendrocyte transcription factor 2, histone H3K27M mutant protein, alpha-thalassemia/mental retardation syndrome X, S-100 and Vimentin, but negative for IDH1 R132H, Syn and NeuN." (PMID 35713454, 2022).